KEAP1 (kelch like ECH associated protein 1)
Diseases named in the same sentence as KEAP1 in open-access papers (continued):
Sharing a sentence is not in itself a finding about the gene and the disease.
cancer (continued). "In the last 10 years, there have been several publications that indicated cancer as being closely connected to the NRF2/KEAP1 signaling pathway." (PMID 33925605, 2021). "This section provides information on the role of the NRF2/KEAP1 axis in the regulation of the cancer metabolism against the cancer redox homeostasis and metabolic mechanisms." (PMID 33922165, 2021). "The rapid progression of patients carrying abnormalities in the Keap1-Nrf2 pathway in other cancer types was reported in several studies." (PMID 35548450, 2021). "The Keap1–Nrf2 pathway is therefore, considered to be a novel oncogenic signalling pathway and an attractive target for developing anti-cancer therapeutics." (PMID 33441941, 2021). "Cancer cells can reduce ROS levels by increasing the expression of antioxidants, notably following inactivation of the KEAP1 tumor suppressor gene, an event observed in 15–30% of cancers." (PMID 34204734, 2021). "Recent studies have reported that KEAP1/NFE2L2/CUL3 mutated in many cancers and led to worse survival outcomes in many cancers, our survival analysis also confirmed this." (PMID 34617407, 2021). "The results demonstrate that KEAP1 mutations activate the NRF2 antioxidant program and promote LUAD progression in concert with mutant KRAS, demonstrating that cancer cells can overcome oxidative stress barriers during tumorigenesis." (PMID 35070984, 2021). "Somatic mutations within Keap1 or Nrf2 (exclusively found in the DLG and ETGE motifs) are the most frequent causes of hyperactive Nrf2 in cancer." (PMID 33895141, 2021). "Several recent studies have suggested that Keap1-Nrf2 is a promising target for the discovery of drugs that prevent various murine and human cancers." (PMID 34200419, 2021). "Another mechanism involved in Nrf2 overexpression in chemoresistant cancers is the rate of degradation, depending on the balancing between ubiquitination and deubiquitination of Keap1 and Nrf2 proteins." (PMID 33805928, 2021). "The NRF2-Kelch-like ECH-Associating protein 1 (Keap1), as well as the NRF2-antioxidant response element (ARE), can counteract the harmful effects of reactive oxidants in cancer cells and restore redox balance to promote cancer adaptation." (PMID 33514437, 2021). "It is known that IR kills cancer cells due to double-stranded DNA damage induced by ROS and the KEAP1 deletion (and consequent activation of NRF2) therefore leads to ROS suppression." (PMID 36046142, 2021). "Multiple Nrf2 or Keap1 inhibitors have been reported; and some of them are in the stages of pre- and clinical trial towards the Nrf2 signaling for cancers." (PMID 33841137, 2021). "The compound reduces cancer cells proliferation, survival and migration through multiple signaling pathways, notably via modulation of the NFκB, Keap1/Nrf2 and HIF1α pathways." (PMID 34680439, 2021). "In this study, we also found KEAP1 was significantly downregulated in LUAD cancer tissues and knockdown of KEAP1 enhance the NRF2 expression." (PMID 34136401, 2021). "The Keap1-Nrf2 system plays a crucial role in mediating the oxidative stress response, which also contributes to cancer progression." (PMID 33672789, 2021). "Here, we were able to test this observation in the cancer cell line A549-shPERK that shows high levels of cellular NRF2 due to a dysfunctional Keap1 protein." (PMID 33441543, 2021). "Recent studies have established that Nrf2/Keap1 signaling has a key role in the development of cancers including GC." (PMID 34098867, 2021). "It is becoming clear that the NRF2/KEAP1 pathway plays an important role in exerting the metabolic reprogramming of cancer cells through a transcriptional program inducing the proliferation of cancer cells and malignant progression." (PMID 33922165, 2021). "In conclusion, we showed that the activation of the p62/Keap1/NRF2 pathway can play a pro-tumorigenic role lowering cancer cell sensitivity to death-inducing drugs such as Zn(II)–curc." (PMID 33669070, 2021).
cancer (continued). "The KEAP1-NRF2 pathway played vital roles in regulation of cancer progression and recent studies indicated that dysfunction of KEAP1 was cooperated to drive LUAD initiation and correlated with poor survival in patients." (PMID 34226519, 2021). "Somatic mutations in the DLG and ETGE motifs of Nrf2, with very high frequency, occur in numerous cancer cells, leading to the disruption of the two-site binding of Keap1–Nrf2 and constitutive accumulation of Nrf2." (PMID 35052602, 2021). "By the effect of oxidative stress or anti-cancer compounds, the cysteine residues of KEAP1 are chemically modified leading to degradation of NRF2." (PMID 33808001, 2021). "It is noteworthy that the NRF2/KEAP1 signaling pathway has previously been shown to play a critical role in tumorigenesis and the correlation between redox and metabolism in cancer." (PMID 33922165, 2021). "Apart from them, the alternation of Kelch‐like ECH‐associated protein 1 (KEAP1) gene, encoding the KEAP1, has been found to be associated with LUAD with a frequency of 23% and therefore is considered a cancer driver gene." (PMID 34328274, 2021). "The dual roles of the KEAP1-NRF2 pathway in preventing or initiating pancreatic cancer primarily depend on the stages of cancer and the states of KEAP1 and NRF2." (PMID 33845796, 2021). "Specifically, Neh2 acts as a negative regulator of Keap1, and the regulation of Nrf2 levels by Keap1 is abrogated in human cancers." (PMID 33466626, 2021). "In fact, in many cancer cells the Keap1-mediated Nrf2 downregulation is abolished or diminished, thus generating an addiction to Nrf2 and, thereby, favoring cancer cell defenses and progression." (PMID 33801098, 2021). "Nrf2 is a key regulator of metabolism in cancer cells: Cancer cells acquire a resistance to oxidative, metabolic, and therapeutic insults through Nrf2/Keap1 signaling, which results in cytoprotective responses." (PMID 33466626, 2021). "Inactivating mutations in KEAP1 gene occur frequently in many cancer types and largely affect the NRF2-KEAP1 interaction." (PMID 33808001, 2021). "Suppression of the expression level of Nrf2 via applying a CRISPR/Cas9 genome editing system illustrated that ERBB3 and IGF1R signaling pathway accompanied by thioredoxin and peroxiredoxin proteins play an effective role in KEAP1-mutant cancer cells." (PMID 33768092, 2021). "According to previous studies, the dysregulation of the p62/Keap1/Nrf2 axis affected cancer development." (PMID 32718084, 2020). "A significant portion of cancer‐associated mutations in KEAP1 inhibits its ubiquitin ligase activity toward SOX9 and these mutations promote cancer cell growth and tumorigenesis through the stabilization of SOX9." (PMID 33173725, 2020). "These eight transcripts were linked to the following cancer‐related genes: TRIM33, USP6, PRDM16, SETD1B, MLLT3, KEAP1, CHD2, and DCAF12L2." (PMID 32821278, 2020). "In various cancers, somatic mutations in the NRF2-interacting KEAP1-DC or the degron Neh2 have been reported." (PMID 32823937, 2020). "Research has now shown that mutations in KEAP1 and NFE2L2 are often associated with late-stage metastatic disease, with stage-4 cancer patients showing higher NRF2 activity than stage-3 patients." (PMID 33276631, 2020). "The function of Keap1 (Kelch-like ECH-associated protein 1), a sensor of oxidative and electrophilic stress, in the radiosensitivity of cancer cells remains elusive." (PMID 33087706, 2020). "Although large-scale genomic studies have identified the frequent mutations in KEAP1/NRF2/ CUL3 pathway and their prominent roles in LUSC and other cancers, less attention is paid on their complicated down-stream effects." (PMID 32434476, 2020).
cancer (continued). "This calls for further investigation in different cancer scenarios to better characterize the epigenetic regulation of Nrf2/Keap1 by phytochemicals." (PMID 32938017, 2020). "KEAP1/NFE2L2, a cellular pathway for sensing and responding to oxidative stress, is frequently mutated in human cancers." (PMID 32839463, 2020). "By using ARE reporter plasmids, miR-432-3p was supposed to promote the NRF2 protein stabilization by directly binding the KEAP1 coding region, thus increasing the resistance of cancer cells to cisplatin (CDDP)." (PMID 33287295, 2020). "There are a tremendous number of reports that show somatic mutations in the KEAP1 and NRF2 genes in cancers that originated in various tissues, and their frequencies are especially high in non-small cell lung carcinomas." (PMID 33375248, 2020). "K67, a compound that interferes with the interaction between phospho-p62 and Keap1, resulting in the restoration of the Keap1-Nrf2 binding, has been shown to render cancer cells sensitive to anti-cancer drugs." (PMID 33053665, 2020). "The discoveries of somatic mutations in the KEAP1 and NRF2 genes and NRF2-addicted cancers established other lines of important cancer-related studies related to the KEAP1–NRF2 system; therefore, this system has become very popular in cancer science." (PMID 33375248, 2020). "The Keap1/Nrf2 system has been shown to be, on the one hand, critical for cell survival and, on the other hand, dysregulated in cancer." (PMID 33087706, 2020). "miR-200a downregulates KEAP1 in several cancer types including HCC and it promotes induced expression of NQO-1 and GSTA-4, and GCLC genes which are the direct target of NRF2." (PMID 32751080, 2020). "In KLK LUAD, KEAP1 mutation leads to NRF2 activation, which influences many of the hallmarks of cancer and confers “NRF2 addition”." (PMID 33299528, 2020). "In many human cancer cells, the KEAP1-mediated regulation of NRF2 activity is abrogated, resulting in the persistent activation of NRF2." (PMID 32112372, 2020). "Concomitantly, it is of utmost importance to determine the specific pathways and the equilibrium between ROS and NRF2 so as to elucidate the paradoxical role of KEAP1/NRF2 pathway in cancer." (PMID 32106613, 2020). "Up until the discoveries of NRF2 and KEAP1, the mechanism by which cancer chemopreventive agents induce gene expression was the subject of considerable conjecture." (PMID 33276631, 2020). "Downregulation of KEAP1 (KLHL19), the most well-studied KLHL family gene, is implicated in many types of cancer, and cancer-associated mutation of other KLHL family genes has been described." (PMID 33182325, 2020). "Abnormalities of Keap1-Nrf2 pathway lead to a mechanism of oncogenesis and chemo- and radio-resistance in a variety of cancers including HNSCC4." (PMID 32814771, 2020). "Epigenetic modifications have been widely described to impact on the modulation of the KEAP1/NRF2 system in cancer." (PMID 33287295, 2020). "Functional investigation reveals that TRIM25 facilitates tumor cell survival by targeting Keap1 for ubiquitination and degradation, leading to activate Nrf2 signaling and reduce ROS levels during ER stress in several cellular models of cancers." (PMID 31953436, 2020). "Gain-of-function mutations in NRF2 and loss-of-function mutations in KEAP1 are found in certain cancers, resulting in high constitutive levels of NRF2, an example of how cancer cells hijack the NRF2 protective response." (PMID 32053600, 2020). "The mechanism of sustained NRF2 activation has been revealed in some hereditary cancer types and is related to the effects on genes coding for metabolic enzymes which can in turn affect key cysteine residues on KEAP1 to disrupt NRF2 interaction." (PMID 32443774, 2020). "Cancer-associated NRF2 mutation hot spots in the N-terminal region, which are crucial for the interaction with the redox sensor KEAP1, result in a gain of function and cancer development (top)." (PMID 32123008, 2020).
cancer (continued). "An increase of Nrf2 pathway activation, resulting from the disruption of KEAP1/CUL3/RBX1 E3-ubiquitin ligase complex is observed in many cancers and potentially leads to chemoresistance." (PMID 32346533, 2020). "The interactions between Nrf2 and Keap1 are inhibited by somatic mutations acquired in the Nrf2, CUL3 and/or Keap1 genes in cancer cells." (PMID 33050575, 2020). "Aberrant Keap1-Nrf2 signaling leads to radio- and chemoresistance and provides a growth advantage to cancer cells, due to the constitutive expression of cytoprotective genes." (PMID 32148493, 2020). "As for the intragenic CpGs island of many cancer-related genes, the function of CpGs located in the gene body of KEAP1 has been poorly investigated." (PMID 32971994, 2020). "Together, these results suggest that etoposide can suppress cancer cell proliferation by promoting the degradation of SOX9 in a KEAP1‐ and CKIγ‐dependent manner." (PMID 33173725, 2020). "Knockdown of Keap1 using specific small-interfering RNA (siRNA) showed a similar outcome, suggesting an essential role of Keap1 in cancer cell radiosensitivity." (PMID 33087706, 2020). "Keap1–Nrf2 is a well-known defense system against cellular oxidative stress which is frequently observed in cancer progression." (PMID 33142954, 2020). "KEAP1, and NFE2L2 somatic mutations have been identified and characterized in various human cancers, including lung, liver, renal, and squamous cell cancers, leukemia, and others." (PMID 31428048, 2019). "Being located at the crossroad of multiple defensive responses influencing cell fate during xenobiotic, oxidative, and metabolic stress, the NRF2/KEAP1 pathway has been the focus of extensive research aimed at elucidating its impact in cancer." (PMID 31097977, 2019). "KEAP1/Nrf2 pathway inactivation (through KEAP1 or Nrf2 mutations for example) can be a poor prognostic factor for HCC treatment and help clinicians predict the characteristics of specific cancers." (PMID 31903165, 2019). "KEAP1 inactivated in multiple cancers including thoracic and endometrial; also hasoncogenic role, CDDO-Me used forleukaemia and sold tumours." (PMID 31287417, 2019). "Oncogenic character of Nrf2 at the early stages of cancer encourages the researchers to design new inhibitors of Nrf2/Keap1-signaling pathway." (PMID 31022969, 2019). "The dysregulation of Keap1/Nrf2 signaling promotes the dual roles of Nrf2 in cancer, being considered a tumor suppressor and a target oncogene." (PMID 31998662, 2019). "In some cancers, ROS levels are suppressed by continuous activation of NRF2 achieved via mutations in NRF2 or its inhibitors KEAP1 that prevents NRF2 translocation from nucleus to cytoplasm." (PMID 31717786, 2019). "NRF2 tends to be overexpressed in cancers when it is freed from KEAP1 anchoring in the cytoplasm at the oxidative state and then translocates to the nucleus, where it heterodimerizes with sMAF and binds to ARE." (PMID 35582567, 2019). "Many studies have also tried to elucidate the potential role of ER stress in the regulation of the NRF2/KEAP1 pathway, since this condition is frequently found in cancer cells exposed to nutrient deprivation, hypoxia, radiotherapy, and chemotherapy." (PMID 31097977, 2019). "In this study, we showed for the first time that K‐563 exerted Keap1/Nrf2 pathway inhibition and potent anti‐proliferative effects against cancer cells." (PMID 30735010, 2019). "In the following sections, we will discuss the oncogenic alterations in the NRF2/KEAP1 pathway that confer a selective advantage to malignant cells and their relevance as therapeutic targets in the treatment of cancer." (PMID 31097977, 2019).
cancer (continued). "We subsequently investigated how JNK1 affects the Keap1-dependent degradation of Nrf2 in QC-treated cancer cells, demonstrating that QC increased the interaction between Nrf2 and Keap1 and that siJNK decreased this interaction in the presence or absence of QC." (PMID 31491980, 2019). "From these reports, the inhibition of the Keap1/Nrf2 pathway is important for improving the drug sensitivity in cancers resistant to chemotherapy." (PMID 30735010, 2019). "The occurrence of genetic mutations in the NRF2, KEAP1, or CUL3 genes represents the most frequent and well-characterized mechanism of sustained NRF2 activation in cancer." (PMID 31097977, 2019). "There are currently several approaches being developed to target aberrant CYS metabolism in cancer, including NRF2/KEAP1 mutant cancer." (PMID 31107239, 2019). "Recently, epigenetic silencing of Keap1 gene has been observed in many cancers to promote the accumulation of NRF2." (PMID 30811526, 2019). "In many cancers, the general methylation pattern of the DNA is changed, and the promoter region of Keap1 becomes hypermethylated, resulting in the decreased transcription of the Keap1 protein and the release of Nrf2." (PMID 31717324, 2019). "The different roles of Nrf2 in cancer progression were analyzed in a study from 2016, with Keap1 knockdown mice." (PMID 31717324, 2019). "Treatment with the PPP inhibitor 6-aminonicotinamide (6-AN) abrogated the growth of Keap1-deficient tumor cells, suggesting a potential therapeutic approach to target this subset of KRAS-mutant LUAD cancers." (PMID 31519898, 2019). "AEM1 alone and in combination with chemotherapy has been shown to inhibit the growth of cancer cells harboring mutant Keap1 and constitutively activated Nrf2 in vitro and in vivo." (PMID 31511020, 2019). "Comparative structural and evolutionary analyses revealed that these properties were also found in the functionally-validated shallow pocket of other KREPs including that of the cancer-related KEAP1 protein." (PMID 31337835, 2019). "Evidence indicates that a dysregulated NRF2/KEAP1 system, for example KEAP1 mutation or NRF2 mutation, can be responsible for NRF2 overexpression in cancers leading to enhanced cellular proliferation and chemoresistance." (PMID 35582567, 2019). "In the present study, to identify effective Keap1/Nrf2 pathway inhibitors for cancer therapy, we performed a cell‐based screening assay using a Keap1 mutant non‐small cell lung carcinoma cell line." (PMID 30735010, 2019). "From an epigenetic point of view, the effects produced by KEAP1 hypermethylation on the KEAP1/NRF2 signaling in cancer remain partially understood." (PMID 29643973, 2018). "Cell proliferation in cancer was demonstrated to be cross-regulated by KEAP1/NRF2 and EGFR signaling." (PMID 29643973, 2018). "PBQC promoted the S-glutathionylation of Keap-1 protein, activated Nrf2 and promoted cancer cell apoptosis." (PMID 35538996, 2018). "Genes encoding the Nuclear factor (erythroid-derived 2)-like 2 (NRF2) transcription factor and its negative regulator, Kelch-like ECH-associated protein 1 (KEAP1), are frequently mutated in cancer." (PMID 30150714, 2018). "Cancer chemoprevention mechanisms seem to be mediated through the Keap1–NRF2 pathway, and in experimental models, NRF2/Keap1 mutations are present at preneoplastic stages." (PMID 30597961, 2018). "Activation of NRF2 or destabilization of NRF2–KEAP1 interaction caused by genetic modifications of NRF2 and KEAP1 has been reported in several cancer types, including those of liver, esophagus, intestine, lung, and breast." (PMID 29740540, 2018).